IL6 (interleukin 6)
Diseases named in the same sentence as IL6 in open-access papers (continued):
Sharing a sentence is not in itself a finding about the gene and the disease.
tumor (continued). "Similarly, a specific polysaccharide-peptidoglycan complex (PSPG) from Lactobacillus casei Shirota was shown to limit tumor growth by inhibiting the IL-6/STAT3 signaling pathway." (PMID 38288125, 2023). "IL-6 is a pro-inflammatory cytokine that may contribute to tumor progression by stimulating angiogenesis, invasion, and metastasis." (PMID 38022654, 2023). "Our findings demonstrate that curcumin enhances the abscopal effect in a bilateral CT26 tumor-bearing mouse model by suppressing NF-κB and downstream proteins, elevating IL-1β and IL-6, and modulating the overall tumor immune microenvironment, thereby enhancing tumor suppression." (PMID 37242761, 2023). "Moreover, IL-6 upregulates the expression of C-motif chemokine receptor (CCR) 5 on MDSC leading to their recruitment to the tumor site and enhanced inhibitory activity towards CD8+ T cells." (PMID 36860876, 2023). "In this line, EVs derived from heat-stressed tumor cells expressing HSP70 are highly endocytosed by DCs, inducing the synthesis of IL-6 and the differentiation of Treg cells to a type 17 Th cell with the synthesis of IL-17, reducing tumor growth in a prostate cancer model." (PMID 37175226, 2023). "IFN-γ induces the release of IL-6 and IL-8 and promotes anti-tumour response." (PMID 38137361, 2023). "Notably, the same tumor-promoting effects were observed in using the IL-6-abundant CM from AT-MSC to co-culture Ishikawa cells in vitro and in vivo." (PMID 38049868, 2023). "Moreover, the involvement of IL-6 in multiple signal transduction pathways regulating survival, cell proliferation, angiogenesis, tumour development and progression by the expression of several genes indicates an important role in cancer." (PMID 37753372, 2023). "Dissecting whether NA action directly impinges on the tumor, we found that tumors from both treated and untreated animals presented similar levels of Il6 and Inhba transcripts, indicative of unaffected cytokine production by the tumor." (PMID 37012289, 2023). "High serum IL-6 levels correlate with tumor stage and poor survival." (PMID 36693957, 2023). "It has been shown that immunogenic DCs secrete substantial quantities of inflammatory cytokines, including TNF-α, IL-12, IL-6, and IL-8, which may improve the clinical outcomes of tumor patients." (PMID 37513975, 2023). "In addition, deletion of tumor-derived IL-6 in the Kindlin-1-depleted tumors reversed the reduction of tumor-infiltrating Tregs." (PMID 36883731, 2023). "Here, we explore whether an anti-IL-6 receptor antibody could be used as systemic therapy to treat cancer, and further investigate the mechanisms by which IL-6 induces tumor immunosuppression." (PMID 36764954, 2023). "Targeting IL-6 by genetic ablation or pharmacological inhibition in combination with CD40 stimulation or PD-1/PD-L1 signaling blockade improves T-cell infiltration into tumor and enhances mouse survival." (PMID 37114049, 2023). "Although the molecular mechanism of SC-1 action needs to be further clarified, our data strongly suggest that SC-1 inhibits IL-6 production and will provide additional benefit in the management of the disease, which prevents tumor cells resistant to the TGFβ’s tumor suppression activity in cancers." (PMID 37511415, 2023). "The study also showed that GBP therapy caused an increase in IL-6 and MCP-1 serum levels that affect chemotaxis and macrophage activation, which may reduce tumor growth." (PMID 36835284, 2023). "IL-6 can promote the invasive ability of cancer cells, which leads to tumor metastasis." (PMID 37020871, 2023). "The mechanism may be that ACTA2 stimulates the release of IL-6 from tumor-associated fibroblasts (CAF), induces epithelial-mesenchymal transformation (EMT), and induces the transformation from non-invasive tumor type to invasive tumor type." (PMID 37274283, 2023). "Inflammatory cytokines IL-1 and IL-6, secreted by tumor and stromal cells, could induce the rise of CRP." (PMID 38053048, 2023).
tumor (continued). "IL-6 acts either by affecting the tumor cells directly or modulating the tumor microenvironment." (PMID 36495330, 2023). "Glial cells located near the periaqueductal gray matter (PAG) of the midbrain are also activated in tumor-bearing mice, and a several cytokines such as IL-1 and IL-6 are secreted to activate the PI3K-AKT pathway in PAG, leading to central sensitization and cancer pain." (PMID 37007073, 2023). "As an androgen-regulated tumor suppressor miRNA, the attenuation of miR-760 induces the proliferation and growth of PCa cell lines, primarily by targeting and inhibiting the expression of interleukin-6 (IL-6)." (PMID 36608541, 2023). "In addition to this, other works have highlighted the use of interleukin-6 (IL-6) and cytotoxic T-lymphocyte-associated antigen 4 (CTLA-4) levels and tumour burden to predict the occurrence of irAEs." (PMID 37324003, 2023). "In this scenario, adding a laparotomy procedure to the minimally invasive removal of the primary tumor from the animals caused an increase in IL-6 and IL-8 levels, elevated NF-κB, reduced IRF1 activity in excised tumor transcriptomes and initiated an outbreak of micrometastases." (PMID 37296983, 2023). "Furthermore, tumor cell-derived IL-6 and IL-8 activate molecular signals in NK cells that reduce the expression of activation markers (NKp30, NKG2D, and granzyme B), thereby impairing NK cell function." (PMID 37759302, 2023). "Prior studies have indicated that TNFα, IL-1β, IL-6 promote tumor growth in obese mouse models." (PMID 37954072, 2023). "In OSM-knockout mice, cSCC tumor volume was reduced by approximately 30% when compared to wild-type mice after one month, however there were still significant amounts of IL-6, IL-1β, IL-23α, CXCL1, IL-4, and IFNγ present in the tumor tissue compared to normal skin." (PMID 37841259, 2023). "Many experiments have stated that cytokines are not only released by the immune cells occurring in the tumor microenvironment, but an autocrine source of some inflammatory cytokines (IL-1, IL-4, IL-6 and IL-8) was also confirmed in a large spectrum of solid tumors." (PMID 37763324, 2023). "The decrease in CD40 expression levels can down-regulate VEGF, IL-6, and other factors, reducing the risk of CSCC by promoting endothelial cell apoptosis, inhibiting the growth of vascular endothelial cells, and inhibiting tumor angiogenesis." (PMID 37691121, 2023). "In PitNETs, IL6 may contribute to hormone release, to tumor growth and proliferation, and to the production of angiogenic factors, such as vascular endothelial growth factor-A (VEGF-A)." (PMID 37958474, 2023). "Furthermore, we co-cultured microglia with tumor cells and measured the cytokines IL-10 and IL-6, characteristic for M2 and M1, respectively, upon SKI-II administration." (PMID 36672428, 2023). "IL-6 could in turn promote the tumor-promoting function, prolong the lifespan, and maintains the activated state of neutrophils." (PMID 37644468, 2023). "Considering that silencing of E6-HPV has been shown to reduce IL-6 expression, and tumor formation in SiHa and HeLa cells, we expected that the observed AM-dependent down-regulation of E6/E7 expression would be linked to reduced IL-6 expression, but this was not the case." (PMID 36769377, 2023). "Their tumor-bearing mice models showed that IL-6 blockade improves ICB-induced antitumor efficacy." (PMID 37605139, 2023). "Furthermore, derivatives 3 and 21 induced apoptosis/necrosis in PC3 cells,probably by increasing the intracellular ROS amount, as well as theydiminished the IL-6 level in tumor cells." (PMID 37273589, 2023).
tumor (continued). "In this study, DABE also showed mild suppression of tumor growth and decreased plasma IL-6 and MMP-2 levels, suggesting that the PAR1 and PAR4 pathways may also be involved in Colon26 cell proliferation and inflammation induced by Colon26 cells to some extent." (PMID 36751299, 2023). "IL-6 is a pro-inflammatory cytokine produced by tumor cells and tumor-infiltrating immune cells, and therefore increased IL-6 expression indicates local tumor status." (PMID 37298699, 2023). "IL6 trans-signaling enhances T-cell transmigration on tumor vessels." (PMID 37069585, 2023). "Therefore, IL-6/IL-6R is a target for cancer therapies by using antagonists, monoclonal antibodies, or shRNA, suppressing cancer stem cells, colony formation, and tumor development." (PMID 36794014, 2023). "Il-6 has been found to affect immune cell populations which impact tumor development." (PMID 36823670, 2023). "In addition, GSEA analyses revealed that in the high-COL5A2 expression group, tumor progression-related pathways, including angiogenesis, IL6-JAK-STAT3 signaling as well as Notch signaling were enriched." (PMID 37723519, 2023). "Moreover, FABP5 promotes tumor angiogenesis and activates the IL6/STAT3/VEGFA pathway in HCC, as evidenced by studies." (PMID 37576389, 2023). "In addition, IL-1α mediates paracrine senescence in neighboring cells to suppress tumor progression, and IL-1α, IL-6, and IL-8 mediate the recruitment of M1-like macrophages, T helper 1 cells, and NKs to the TME." (PMID 36945046, 2023). "Because IL-6 is a crucial regulator of MDSC activity and proliferation, leading to tumor cell survival, coupled with upregulated IL-6 in the serum of naïve CB2−/− females, we assessed the mRNA expression of IL-6 in the TME along with arginase-1 (Arg1), a functional marker of MDSCs." (PMID 36835468, 2023). "In addition, in recent years, it has been observed in murine models that NK cells can suppress tumor cell growth through the mobilization of epinephrine- and IL-6-dependent cytotoxic NK cells secreted during exercise." (PMID 37888516, 2023). "IL-6 is one of the main pro-tumor cytokines, showing mainly immunosuppressive properties." (PMID 37509653, 2023). "In addition, IL-6/JAK/STAT3 signaling has been demonstrated to play important roles in tumor progression and aggressiveness in several cancers." (PMID 37488213, 2023). "The general mechanism of metastatic bone disease is the development of bone loss by the activation of osteoclasts via pro-osteoclast factors (IL-6, receptor activator of nuclear factor kappa-Β ligand, and parathyroid hormone-related protein) secreted by tumor cells." (PMID 36831154, 2023). "IL-6 is the crucial factor stimulating tumor cell proliferation, survival, and metastasis." (PMID 37958406, 2023). "In addition, IL‐6 is up‐regulated in most of tumour patients and plays an important role in the modulation of these immunosuppressive cells." (PMID 36419386, 2023). "Similarly, the role of neutrophils in tumourigenesis is to secrete high levels of vascular endothelial growth factor, IL-1 and IL-6, which in turn promote the production of tumor blood vessels, leading to tumor growth, development and metastasis." (PMID 37809083, 2023). "Notably, in breast cancer, Th-17 cells are positively related to IL-6, IL-1β, and IL-17 expression and negatively correlated with increased metastatic lymph nodes and tumor cell angiogenesis." (PMID 36993955, 2023). "Tumor microenvironment, such as hypoxia, the presence of IL-6 and other inflammatory factors, may promote the expression of lncRNA in MDSCs." (PMID 36817434, 2023). "IL-6 mediates chronic inflammation and provides a favorable microenvironment for tumor growth." (PMID 37127625, 2023). "Loss of tumor-derived IL-6 drives changes in Treg numbers and function but is not sufficient to reverse clearance of Kin1-NULL tumors." (PMID 36883731, 2023).
tumor (continued). "In addition, MCs actively participate in tumor cell clearance and tumor rejection through the release of IL-1, IL-4, IL-6, and TNF-α." (PMID 37275909, 2023). "Moreover, many studies have confirmed that the second-ranked gene interleukin IL6 was also an important multi-functional cytokine involved in tumour growth and metastasis." (PMID 36945884, 2023). "However, the high expression of YAP in tumor cells induces an increase in IL-6 secretion, which plays an opposite role in tumor progression." (PMID 37663266, 2023). "The mechanisms of tumor-induced neutrophilia are unclear, but tumor-derived cytokines such as G-CSF, IL-1 and IL-6 may stimulate granulopoiesis or neutrophil development." (PMID 37376417, 2023). "IL-6 Figures tumor growth by mobilizing anti-tumor T-cell immune response to control tumor growth." (PMID 37445686, 2023). "IL-6 plays a role in cancer cell proliferation, whereas G-CSF mediates tumor immunosuppression." (PMID 37699010, 2023). "These three types can be separated by the biomarkers of myCAF, which exhibits the high expression of ACTA2, FAP, and TGF-β, and low expression of IL6, which requires direct interaction with cancer cells in PDAC and might be associated with tumor progression." (PMID 36900272, 2023). "This decrease was also reflected in IL-6 levels from tumor extracts as quantified by RT-PCR." (PMID 37397366, 2023). "In this model, CR significantly suppressed tumor IL-6 levels compared to tumor-bearing mice." (PMID 37240117, 2023). "Tumor-derived long intergenic non-coding RNA-482 (LINC00482) was shown to increase levels of pro-inflammatory cytokines such as IL-6, tumor necrosis factor alpha (TNFα), and IL-1 beta (IL-1β), as well as VEGF, which led to increased inflammation and angiogenesis." (PMID 37569686, 2023). "The results of this study indicated that changes of IL-6 and IL-8 in the tumor microenvironments were closely related to the diseases status and may be used as a potential diagnostic or biomarker in canine mammary gland tumors." (PMID 36693957, 2023). "The immunofluorescent staining of IL-6 in tumor sections displayed similar results." (PMID 37752555, 2023). "Additionally, our cytokine analysis determined an uplifted level of inflammatory cytokines, such as VEGF, IL-6, and CCL2, that can cause the progression of the tumor and initiate CRS, which limits the treatment and has a negative impact on the outcome." (PMID 37112810, 2023). "Furthermore, IL-6 favors tumorigenesis by creating an immunosuppressive tumor microenvironment, as the induction of JAK/STAT3 signaling has an inhibitory effect on, for example, dendritic cells, effector T cells, and natural killer cells." (PMID 38250802, 2023). "IL-6 is a pleiotropic cytokine that induces immune tolerance to tumour antigens." (PMID 38414933, 2023). "Besides the infiltrating immune cells, cytokines such as IL-6 are also correlated with tumor progression." (PMID 37174085, 2023). "Tumor-induced secretion of IL-6 fosters skeletal muscle wasting, leading to cancer cachexia." (PMID 37760634, 2023). "However, IL-6 administration increased both the size of primary tumor and the number of metastatic lung lesions, which were reduced by adipocytes-Grem2." (PMID 37880751, 2023). "In the process of non-small cell bone metastasis, the activity of tumor secretory factors (such as IL-1, IL-6 and TNF-α) leads to excessive formation of osteoclasts, induces mobilization of bone marrow-derived cells that promote angiogenesis and tumor homing, and finally promotes tumor growth." (PMID 37652923, 2023). "In summary, our study demonstrated that activation of IL-6/STAT3/SAA signaling by hepatocyte SGK1 in response to IR promotes the formation of a pre-metastatic niche in the liver of CRC, and that tumor-associated NETs and PMN-MDSCs participate in the formation of CRC in an SGK1-dependent manner." (PMID 36788538, 2023).
tumor (continued). "The IL-6 antibody could well neutralize the IL-6 level in the blood, but only played a slight anti-tumor effect, which was consistent with previous reports." (PMID 36969873, 2023). "IL‐6 represents an essential trigger for CAC development in CHX207‐tumour‐bearing mice." (PMID 36351437, 2023). "In addition, in a murine model of breast cancer, the production of IL-6 from adipocytes and tumor-infiltrating myeloid cells, such as macrophages, has been demonstrated to contribute, at least partly, to refractoriness to anti-VEGF treatment." (PMID 36901858, 2023). "Multiple in vitro studies have demonstrated that the process of epithelial-to-mesenchymal transition (EMT), a pivotal step for cancer progression with tumor invasion and distant metastasis, is activated by proinflammatory cytokines including TNFα, IL-6, IL-8, and IL-1β." (PMID 37628724, 2023). "By contrast, other studies speculate that MCs may promote inflammation, inhibition of tumor cell growth, and tumor cell apoptosis by releasing mediators such as IL-1, IL-4, IL-6, IL-8, Mcpt3, Mcpt4, INF-y, TNF-α, TGF-β, LTB4, and chymase." (PMID 37686555, 2023). "An analysis of the outcomes allows us to conclude that female dogs with mammary neoplasia have metabolic changes in the preoperative period possible due to tumor development and progression, including increased blood concentrations of lactate, glucose, fibrinogen, and interleukin-6." (PMID 36899784, 2023). "Moreover, IL10 can also stimulate IL6 expression and synthesis, which can also support tumor progression, and, naturally, already oversecreted by MSCs." (PMID 36661524, 2023). "IL-6 plays a major role in the accumulation and activation of MDSCs during tumor development." (PMID 37006306, 2023). "Increased levels of IL6, both in circulation and at the tumor site, have been demonstrated in BC." (PMID 37238004, 2023). "HNSCC tumor cells produce IL-6, CXCL8, and epidermal growth factor (EGF), which improve the survival and angiogenic potential of endothelial cells through the activation of the STAT3/protein kinase B (AKT)/extracellular signal-regulated kinase (ERK) signaling pathways." (PMID 38003931, 2023). "We postulated that CAF-secreted IL-6 may regulate cell motility via EMT since EMT is essential for tumor invasion and metastasis." (PMID 37941042, 2023). "Based on these recent observations, we hypothesized that elevated baseline IL-6 in blood and tumor tissue is an adverse prognostic marker in NSCLC treated with ICIs and has therapeutic implications." (PMID 37852738, 2023). "Researchers have found that low-dose radiotherapy of the tumor bed may increase the expression of IL-17A and promote invasive growth of the tumor by producing IL-6 and TGF- β." (PMID 37609436, 2023). "In addition, IL-6 and IL-8 released by CAFs not only promote cancer cell invasion but also participate in tumor angiogenesis." (PMID 37666813, 2023). "Interestingly, IL-6 levels in the supernatants were approximately two times higher when GM-CSF BMDC were stimulated alone compared to the tumor cell co-cultures." (PMID 36913398, 2023). "IL-6 induces osteoclast differentiation and increases osteolysis to expand the tumor burden." (PMID 36831154, 2023). "Histological analysis was performed to verify IL-6 production by the tumour." (PMID 38098074, 2023). "It is well known that aberrant overexpression of IL-6 drives the formation of the tumor microenvironment, and OS tumor cells produce large amounts of soluble IL-6, accompanied by increased phosphorylation of STAT3, and exhibit strong chemotaxis to those factors." (PMID 37404767, 2023). "Changes in IL-6 levels have been also observed after tumour removal surgery or during chemotherapy, which might be an indicator of therapy response." (PMID 37794245, 2023). "In addition, lncSNHG can regulate the expression of immune checkpoints such as PD-L1, CD73 and cytokines such as TGF-β and IL-6 to participate in anti-tumor immunity." (PMID 37006268, 2023).